BNIP3 (BCL2 interacting protein 3)
Diseases named in the same sentence as BNIP3 in open-access papers (continued):
Sharing a sentence is not in itself a finding about the gene and the disease.
ischemia (16 papers, 2009 to 2026). A hypoperfusion of the BLOOD through an organ or tissue caused by a PATHOLOGIC CONSTRICTION or obstruction of its BLOOD VESSELS, or an absence of BLOOD CIRCULATION. "Similar to the PINK1/Parkin pathway, BNIP3, as a member of the Bcl-2 family, also induces mitophagy in response to ischemia-related stress and participates in the pathological and protective processes of IRI." (PMID 41451126, 2025). "TRIM2 protects male mice from intestinal ischemia-reperfusion injury by marking the pro-death BNIP3 protein for degradation, revealing a potential therapeutic target." (PMID 40883557, 2025). "Previous studies of UCCAO mouse models have indicated the upregulation of inflammatory chemokines (Ccl2 and Ccl12) as well as ischemia-related genes (Bnip3, Hsp25, and Vegfa) in the retina, and we found similar results with the STZ UCCAO mice." (PMID 40362622, 2025). "It has been recognized that BNIP3 and BNIP3-mediated programmed death play a critical role in HF, especially during ischemia." (PMID 33681183, 2020). "BNIP3 depletion contributes to the inhibition of ischemia cell apoptosis in post-MI mice." (PMID 33681183, 2020). "Loss of Popdc1 causes an increase in the expression of the proapoptotic BCL2 interacting protein 3 (Bnip3), which may explain the increased vulnerability when null mutant hearts are subjected to ischemia/reperfusion injury." (PMID 28939104, 2017). "Whether increased expression of Bnip3 in response to pathological stimuli, such as ischemia or pressure overload, is beneficial or detrimental remains to be established." (PMID 23568341, 2013). "We postulated that BNIP3 levels might affect brain injury after ischemia." (PMID 36551300, 2022). "Combined with the results of in vivo experiments, these findings indicate that GP17 can regulate the mitochondrial autophagy-related Hif1α-BNIP3 pathway through NAMPT-SIRT1, exerting a neuroprotective effect in the process of hypoxia-ischemia." (PMID 36572901, 2022). "ChIP sequencing analyses also showed that FoxO1 binding to the promoter of pro-apoptotic genes, including Bcl2l11, Fadd, Bnip3, and Pmaip1, was decreased in the presence of ischemia or in C/EBP-β-KI, without concomitant increases in C/EBP-β binding to the promoter." (PMID 39060225, 2024). "Thus, our results suggest that in the differentiated myocardium and in ischemic myocytes EndoG, Bnip3 and Bcl-xL are abundant whereas the expression of the caspase-dependent cell death machinery is silenced and is not re-expressed during ischemia." (PMID 21437288, 2011). "BNIP3/NIX is associated with hypoxia-induced mitophagy, and the levels of BNIP3 and NIX are upregulated by hypoxia-inducible factor (HIF-1α) transcription, suggesting that this pathway may be involved in the brain damage that occurs as a result of the hypoxic ischemia that manifests after stroke." (PMID 34557086, 2021). "Both EndoG and Bnip3, but not Nix, were essential for inducing TUNEL-positive DNA fragmentation in experimental ischemia, which did not involve caspase activity." (PMID 21437288, 2011). "Silencing Bnip3 expression, but not that of Nix, blunted high molecular weight (HMW) and LMW DNA degradation during experimental ischemia." (PMID 21437288, 2011).
myocardial infarction (14 papers, 2015 to 2026). Gross necrosis of the myocardium, as a result of interruption of the blood supply to the area, as in coronary thrombosis. "However, deficiency of BNIP3 expression obstructs the ventricle remodeling process in post-myocardial infarction in mice exposed to ischemia–reperfusion by reducing apoptosis." (PMID 29701696, 2018). "BNIP3-associated mitochondrial death and mitophagy has been shown to cause LV remodeling post myocardial infarction, and targeting/inactive BNIP3 has been a tested rationale in restraining ischemic cardiomyocytes from apoptosis and in cardioprotection against systolic heart failure." (PMID 29701696, 2018). "In the heart, BNIP3-mediated necrosis of cardiac myocytes can contribute to ischemic heart disease, including myocardial infarction." (PMID 38540059, 2024). "In our observation in heart cells, along with the mitochondrial death signaling, BNIP3 also induced an autophagy marker that has been shown to induce LV remodeling post myocardial infarction." (PMID 29701696, 2018). "BNIP3 has been reported to be upregulated in the heart after acute ischemia and in chronic heart failure patients after myocardial infarction." (PMID 26000071, 2015). "We focused on cardiac mitophagy during and following myocardial infarction by highlighting the role and the regulation of PI NK1/parkin-; FUNDC1-; BNIP3- and BNIP3L/NIX-induced mitophagy during ischemia and reperfusion." (PMID 35053316, 2022). "A recent study demonstrated, with a myocardial infarction model, that the beneficial effects of MSC transplantation are mediated by exosomes, which shuttled miR-125b-5p by targeting Bnip3." (PMID 32019561, 2020). "Additionally, after BNIP3 knockdown, BBR did not decrease the myocardial infarct size." (PMID 32292345, 2020).
heart failure (13 papers, 2015 to 2026). Inability of the heart to pump blood at an adequate rate to meet tissue metabolic requirements. "BNIP3 has been found to be involved in cardiomyocyte apoptosis during heart failure and in doxorubicin-induced cardiomyocyte pyroptosis." (PMID 37737187, 2023). "The involvement of BNIP3 in the pathogenesis of diseases such as heart failure and cancer has been extensively studied before and it is associated with the regulation of mitochondrial turnover and cell death programs like apoptosis and necrosis." (PMID 38011286, 2023). "Overexpression of Bnip3 in transgenic mouse hearts confers increased apoptosis, contractile dysfunction and age-related dilated cardiomyopathy that culminate in heart failure." (PMID 26317696, 2015). "Bnip3-TG mice underwent age-dependent ventricular dilation and heart failure that was partially prevented by p300 inhibition with curcumin." (PMID 26317696, 2015). "Multiple studies have demonstrated elevated autophagy in cardiac myocytes and intact hearts during hypoxia, ischemia, ischemia-reperfusion, and heart failure including roles for Bnip3." (PMID 26317696, 2015). "Moreover, genetic ablation of Bnip3 in mice reduced doxorubicin-induced damage of mitochondria and heart failure rates." (PMID 39285385, 2024). "BNIP3 is a pro-apoptotic gene and correlated with progression towards heart failure, so that its down-regulation might point to a potential early coping mechanism upon stretch." (PMID 35805966, 2022). "Bnip3 is induced in the heart by ischemia and pressure-overload, and may contribute to cardiomyopathy and heart failure." (PMID 26317696, 2015). "In the heart failure group, PINK1 protein expression was significantly down-regulated, Parkin and BNIP3 protein expression were significantly up-regulated, and SKQ1 and aerobic exercise significantly down-regulated Parkin and BNIP3 protein expression." (PMID 40076760, 2025). "To further characterize functional interactions between Bnip3-p300 and GATA4, we measured the transcript level of atrial natriuretic protein (ANP), a gene that is regulated by p300-GATA4 and a marker of heart failure." (PMID 26317696, 2015). "Bnip3-TG hearts expressed high levels of ANP, a p300/GATA4-regulated gene and a marker of DCM and heart failure." (PMID 26317696, 2015).
acute kidney injury (12 papers, 2019 to 2025). Sudden and sustained deterioration of the kidney function characterized by decreased glomerular filtration rate, increased serum creatinine or oliguria. "Hypoxia-inducible factor-1α (HIF-1α)-BNIP3-mediated mitophagy in renal tubular cells attenuates apoptosis and senescence during acute kidney injury (AKI)." (PMID 39456203, 2024). "In the present study, cisplatin upregulated both ferroptosis and mitophagy, specifically autophagy, and genetic inhibition of BNIP3- or PINK1-PARK2-mediated mitophagy resulted in aggravation of ferroptosis in cisplatin-induced acute kidney injury." (PMID 36923942, 2023). "The present study was designed to investigate BNIP3-mediated and PINK1-PARK2-mediated mitophagy and its regulation of ferroptosis in a cisplatin-induced acute kidney injury model using Pink1, Park2 and Bnip3 knockout mice." (PMID 36923942, 2023). "It was reported that HIF1α-BNIP3-mediated mitophagy plays a protective role against ischemia/reperfusion-induced acute kidney injury." (PMID 36928344, 2023). "Further, the present study used Pink1 knockout, Park2 knockout and Bnip3 knockout mice to confirm the protective role of both PINK1-PARK2-mediated and BNIP3-mediated mitophagy in cisplatin-induced acute kidney injury." (PMID 36923942, 2023). "Here, we investigated the mechanism underlying both BNIP3-mediated and PINK1-PARK2-mediated mitophagy-induced attenuation of ferroptosis in cisplatin-induced acute kidney injury." (PMID 36923942, 2023). "To clarify the function of BNIP3 and BNIP3-mediated mitophagy in cisplatin-induced acute kidney injury, we intraperitoneally injected cisplatin into Bnip3 knockout mice." (PMID 36923942, 2023). "BNIP3 has been reported to mediate mitochondrial oxidative stress, apoptosis, and autophagy in acute kidney injury." (PMID 33681182, 2020). "However, BNIP3-mediated mitophagy and the downstream pathway and mechanism are poorly understood in cisplatin-induced acute kidney injury." (PMID 36923942, 2023). "Furthermore, the upregulation of mitophagy induced by activated HIF-1α/BNIP3 signaling pathways was proved to inhibit apoptosis in acute kidney injury." (PMID 37101593, 2023). "However, the concentration of serum creatinine in ischemic KO was significantly higher than in WT mice in the same experimental setting, indicating more severe renal failure in Bnip3-KO mice after renal IR." (PMID 31515472, 2019). "Importantly, Bnip3 knockout, Pink1 knockout and Park2 knockout mice showed more severe kidney injury than WT mice, suggesting the important roles of mitophagy and mitochondrial quality control in cisplatin-induced acute kidney injury." (PMID 36923942, 2023). "HIF-1α knockout attenuates mitophagy, exacerbating ROS accumulation and apoptosis in acute kidney injury (AKI), whereas BNIP3 overexpression rescues this phenotype, highlighting its cytoprotective role." (PMID 40723842, 2025). "In studies on ischemia/reperfusion (I/R)-induced acute kidney injury (AKI), it was found that HIF-1α-BNIP3 can induce mitophagy in HK-2 cells, inhibit apoptosis and ROS production in AKI, thereby exerting a protective effect on the kidney." (PMID 40305351, 2025). "This restoration of BNIP3 was considered protective, which is consistent with Zheng’s report in STZ-induced diabetic rat model and acute kidney injury mouse model induced by renal ischemia/reperfusion injury." (PMID 38697845, 2024). "However, the aggravation of cisplatin-induced acute kidney injury in Bnip3/Pink1/Park2 knockout mice was not attributed to only the pharmacological action of cisplatin, which indicated that mitophagy may have an effect on renal volume." (PMID 36923942, 2023).
breast tumor (12 papers, 2009 to 2025). "Our results showed that samples with higher FTO expression (vs average expression level of FTO in breast tumor tissues) was frequently associated with lower BNIP3 level and vice versa." (PMID 30922314, 2019). "FTO mediated the m6A demethylation of BNIP3 mRNA and induced its degradation, thus promoting breast tumor progression." (PMID 38782769, 2024). "The increased aggressiveness of breast tumors in BNIP3-depleted mice is related to a decrease in mitophagy and the increased stability of HIF1A, indicating that BNIP3 can inhibit HIF1A and mitochondrial dysfunction." (PMID 33262988, 2020). "Our results showed that double knockout cells significantly alleviated the inhibitory effects on tumor growth mediated by FTO deficit, proving that FTO promoted breast tumor growth primarily via modulating BNIP3 expression by the m6A modification." (PMID 30922314, 2019). "Here, we have demonstrated arming of measles virus with BNiP3 to antagonize anti-apoptotic nature of breast tumor cells, enhances its lytic ability as compared to unarmed virus suggesting that BNiP3 contributes to increased apoptosis." (PMID 30697531, 2018). "A more recent study suggested that upregulation of BNIP3 protein expression plays a role in breast tumor progression." (PMID 19505343, 2009). "One study showed high BNIP3 mRNA expression in breast tumors compared to normal tissue, especially in peri-necrotic tumor region." (PMID 19505343, 2009). "By analyzing the data set (GSE9014), we detected the levels of BNIP3 and FTO in normal and breast tumor samples." (PMID 30922314, 2019). "Double knockdown of BNIP3 and FTO promoted breast tumor growth in mice as reflected by the significant increase of tumor size and tumor weight comparing to the stable FTO-knockdown cells." (PMID 30922314, 2019). "To validate their correlation, we performed the immunohistochemistry assay to detect the protein levels of BNIP3 and FTO in our breast tumor sample cohort consisting of 36 primary breast tumor tissues." (PMID 30922314, 2019). "A significant negative correlation between BNIP3 and FTO levels was observed in breast tumors (coefficient = − 0.3083, P = 0.0029)." (PMID 30922314, 2019).
Cerebral ischemia (11 papers, 2014 to 2024). Restriction of arterial blood supply to the brain associated with insufficient oxygenation to support the metabolic requirements of the tissue. "Recent studies indicate that HIF-1α promotes programmed cell death during cerebral ischemia by inducing Bcl-2 family members like BCL2 Interacting Protein 3 (BNIP3), which regulates autophagy nucleation." (PMID 39199193, 2024). "To explore the molecular mechanism of SNHG14 in cerebral ischemia–reperfusion injury, we examined the expression of miR-182-5p and BNIP3 in the OGD/R-induced HT22 cells." (PMID 32912324, 2020). "Studies have extensively investigated the role of BNIP3 in response to heart disease, and cerebral ischemia." (PMID 29708992, 2018). "Bnip3 overexpression can be induced by hypoxiainducible factor (HIF) 1 during the hypoxia condition in cerebral ischemia." (PMID 30501621, 2018). "Changes in Hif-1a expression by the administration of either anti miR-335 or miR-335 mimic in cerebral ischemia were accompanied with the corresponding alteration of the downstream genes Angpt2, Bnip3, Mmp9, Pai1 and Vegfa." (PMID 26030758, 2015). "We previously observed the involvement of EndoG in BNIP3-induced cell death in models of hypoxia and cerebral ischemia." (PMID 25436615, 2014). "It has been proved that BNIP3 overexpression can be mediated by HIF-1α in cerebral ischemia." (PMID 37101593, 2023). "A study had indicated an altered permeability of the nuclear membrane after cerebral ischemia which may initiate abnormal Bnip3 expression, thereby leading to the cell death." (PMID 30501621, 2018). "Bnip3 is a well-known proapoptotic gene which contributes to apoptosis upon cerebral ischemia." (PMID 26030758, 2015). "Since Angpt2, Bnip3, Mmp9, Pai1 and Vegfa genes are also important key players in cerebral ischemia, it is possible that the overall changes in their expression synergistically contribute in bringing about the beneficial effect of miR-335 in reducing the infarct volume." (PMID 26030758, 2015). "We verified the expression of Angpt2, Bnip3, Mmp9, Pai1 and Vegfa genes since they were reported to be regulated by HIF-1α during cerebral ischemia." (PMID 26030758, 2015). "Our findings are consistent with related reports that MCAO/R induces upregulation of Hif1α and BNIP3, suggesting that GP17 may regulate the Hif1α-BNIP3 pathway to mediate autophagy in the acute phase of cerebral ischemia." (PMID 36572901, 2022).
diabetes (11 papers, 2016 to 2025). "Our results demonstrated that KCa3.1 deficiency was able to reverse diabetes-induced mitochondrial dysfunction by normalizing the disrupted mitochondrial quality control, which was likely mediated through inhibition of BNIP3 expression." (PMID 33681190, 2021). "In contrast, BMAL1 overexpression appears to provide renal protection in diabetes by promoting mitophagy via the HIF-1α/BNIP3 signaling pathway." (PMID 40594206, 2025). "The role of autophagy in microvascular remodeling in diabetes is actively discussed, particularly regarding interactions with HIF1α, mTOR, and the Bnip3/FoxO3a axis." (PMID 41169477, 2025). "To determine the effects of celecoxib on autophagy lysosome system in diabetes-induced muscle atrophy, we examined the levels of BNIP3, Beclin1, LC3 II and ATG7 in tibialis anterior." (PMID 38313305, 2024). "Here, we detected diabetes-induced expression of Bnip3 with a further increase by exercise intervention in both wildtype and Ulk1-S555A mice." (PMID 38203804, 2024). "TXNIP inhibition suppressed diabetes-induced BNIP3 expression and activation of the mTOR signaling pathway." (PMID 27381856, 2016). "Moreover, the expression of autophagy-associated proteins C/EBPβ, BNIP3, and LC3 II/I was increased after I/R in the non-diabetes and diabetes groups compared with sham-operated groups." (PMID 33414413, 2021). "KCa3.1 deficiency significantly attenuated diabetes-induced upregulation of BNIP3 expression in diabetic KCa3.1−/− mice (K−/− DM) (P < 0.05)." (PMID 33681190, 2021).
gastric cancer (11 papers, 2009 to 2025). A primary or metastatic malignant neoplasm involving the stomach. "This interaction, along with the downregulation of lncRNA PVT1 and the upregulation of BNIP3 levels, inhibited the proliferation of gastric cancer cells, and clinical evidence demonstrates that BNIP3 upregulation favors the prognosis of cancer patients." (PMID 38397398, 2024). "In gastric cancer, tumor cells partly occur aberrant methylation of BNIP3 but not in adjacent normal tissues, which indicates that inactivation of BNIP3 would promote gastric cancer progress." (PMID 36937439, 2023). "SH003 exerts apoptosis, ER stress, G9a-mediated epigenetic modification, and Bnip3-induced autophagic cell death via the release of ROS on hypoxia exposure in gastric cancer cells." (PMID 36830050, 2023). "Aberrant methylation of BNIP3 was also detected in 66% of primary colorectal and 49% of primary gastric cancers." (PMID 22827957, 2012). "Sixty six percent of the primary colorectal and 49% of the gastric cancers showed BNIP3 methylation." (PMID 19505343, 2009). "BNIP3 (BCL2/adenovirus E1B 19 kDa interacting protein 3) is a proapoptotic member of the Bcl-2 family and its mutation and dysregulation might play a role in gastric carcinoma development." (PMID 22827957, 2012). "The expression of BNIP3 has also been reported to be absent in gastric cancer." (PMID 33194715, 2020).